MPO (myeloperoxidase)
Diseases named in the same sentence as MPO in open-access papers (continued):
Sharing a sentence is not in itself a finding about the gene and the disease.
colitis (continued). "The present results strongly suggest that the treatment with HBO ameliorates TNBS-induced model of colitis and is associated with decreased in the severity of inflammation as measured by MPO, cytokine levels, iNOS and COX-2 expression." (PMID 25926972, 2015). "The i.c. instillation of TNBS caused reproducible colitis in mice, characterized by elevated macroscopic colon damage score and increased MPO activity." (PMID 25743575, 2015). "Although the Lcn2−/− mice exhibited moderate colitis, they were associated with marked reductions in neutrophil infiltration, edema, and MPO activity compared to the rest of the groups 72 h after infection." (PMID 24465207, 2014). "DSS-induced colitis is often associated with increased MPO activity, which is indicative for an increased number of infiltrating neutrophils." (PMID 24787575, 2014). "In controls and in CORT-nursed rats, induction of colitis caused a significant (P<0.01 and P<0.05, respectively) increase in colonic mucosal MPO activity with respect to corresponding healthy rats." (PMID 25405993, 2014). "In the DSS model of colitis, B. infantis feeding was associated with decreased histopathology and decreased MPO levels." (PMID 23704880, 2013). "Restoration of IL-13 levels in IL-13−/− mice were associated with increased severity of DSS-induced colitis and increased levels of MPO activity." (PMID 24015275, 2013). "Oxidative stress is believed to play an important role in the pathogenesis of colitis-related intestinal tissue injury; MPO is a marker of oxidative stress produced mainly by polymorphonuclear leucocytes and is associated with the severity of colitis." (PMID 24451125, 2013). "Reduction in the severity of DSS colitis was associated with significantly lower MPO activity, as well as reduced IL-1β, IL-6 and IL-17 production in IL-13−/− mice." (PMID 24015275, 2013). "To assess the effect of MC-12 on the inflammatory changes associated with experimental colitis, we determined in colon tissue samples the activity of myeloperoxidase and cytosolic phospholipase A2 (cPLA2) as well as the response of five inflammatory cytokines." (PMID 22844504, 2012). "TNFR1 ablation led to exacerbation of signs of colitis, including more weight loss, increased mortality, colon shortening and oedema, severe intestinal damage, and higher levels of myeloperoxidase compared to wild-type counterparts." (PMID 23285227, 2012). "The colitis caused by DNBS was also characterized by an increase in myeloperoxidase activity, an indicator of the neutrophils' accumulation in the colon." (PMID 20671911, 2010). "We found that the loss of MPO significantly enhanced the resolution of DSS-induced colitis." (PMID 39133648, 2024). "In addition, a reduction in colitis severity was associated with significantly lower colonic MPO and IL-1β levels." (PMID 38713616, 2024). "Overall, our findings demonstrate that C:15 has significant anti-inflammatory potential, protecting against colitis by reducing weight loss, fecal MPO activity, and less translocation of FITC dextran, indicating a decrease in inflammation and preserving gut integrity." (PMID 39275347, 2024). "This revealed distinct phylogenetic polarities that are largely maintained with time and differences in the relative abundance of some IBD-associated genera in Wt and MPO KO mice which may influence the course of colitis." (PMID 38673843, 2024). "The relative abundance of the Allobaculum genus was significantly increased in MPO KO mice at Day 29 and this could explain the susceptibility of colitis in MPO KO mice." (PMID 38673843, 2024). "UDCA significantly ameliorated DSS-induced colitis, as evidenced by markedly reduced weight loss, disease activity index score, and shortening of the colon length, and the myeloperoxidase (MPO) concentration in the colon." (PMID 36721210, 2023).
colitis (continued). "The results indicated that the administration of ghrelin significantly ameliorated weight loss and the histological colitis score, improved the survival rate and decreased the myeloperoxidase activity of colonic tissue in ghrelin-administrated mice in comparison with the control group." (PMID 35050153, 2022). "In TNBS-induced colitis in rats that underwent repeated short-term cold restraint, stress-induced colitis severity was associated with increased mucin and goblet cell depletion, along with increased MPO expression." (PMID 34065791, 2021). "Additionally, in vivo studies demonstrated that bLF administration ameliorated the severity of DSS or azoxymethane (AOM)-induced colitis as reflected by reduced body weight loss, decreased colon shortening, and reduced myeloperoxidase (MPO) activity." (PMID 34901112, 2021). "In particular, the polyphenol-enriched Marcona almond blanch water was applied to in vivo rat colitis models, causing a reduction in inflammatory cell infiltrate, together with the inhibition of myeloperoxidase (MPO) activity and other related enzymes, such as iNOS." (PMID 34441570, 2021). "Whether the ability of TRPA1 inhibition and deletion to reduce colitis-associated somatic mechanical hypersensitivity is related to the observed nominal reduction of colonic MPO activity requires further investigation." (PMID 32451393, 2020). "In accord with previous work, such blockade of IL-10 signaling resulted in typical features of colitis, including loss of weight/adiposity, splenomegaly, colomegaly, colon shortening, elevated MPO, increase in pathohistological scoring, and elevations in serum IL-6 and CXCL1." (PMID 31827095, 2019). "Treatment with TNBS causes severe colitis by increasing myeloperoxidase activity." (PMID 28946886, 2017). "The results showed that allergen-related colitis was induced in mice as shown by heavy infiltration of inflammatory cells in the colon mucosa, loss of body weight of mice, increases in myeloperoxidase, tumor necrosis factor-α, interleukin-4, OVA-specific IgE in the colon tissue." (PMID 27604348, 2016). "Above results indicated that DSS-treated mice demonstrated colon injury and acute colitis (mild colitis and sever colitis), including body weight loss, colon length shorten and MPO activity, all of which could be reduced by CK and BBR." (PMID 24504372, 2014). "Furthermore, when 5-HT stimulated DCs are transferred back into TpH1 deficient mice, there is significant increase in colitis severity and this is associated with higher myeloperoxidase (MPO) activity and pro-inflammatory cytokine (IL-1β and IL-6) levels." (PMID 25565996, 2014). "Here, our results demonstrated that the induction of colitis caused a significant increase in myeloperoxidase (MPO) activity, which predominantly existed in neutrophils, monocytes and macrophages, and is currently used as a quantitative index of oxidative stress in colonic mucosa." (PMID 23936328, 2013). "This inability may be related to the nature of the induction of colitis used, which causes such an extensive damage that MPO high levels are strongly sustained, so that it is uncommon for any treatment to exhibit this pharmacological activity." (PMID 23346204, 2012). "The addition of 2.3% DSS to drinking water for 7 days caused colitis with a reduction in body weight and large intestine length, and an increase in the rectum weight, stool consistency/diarrhea score, bleeding score, and rectal MPO activity." (PMID 21853095, 2011). "Furthermore, myeloperoxidase (MPO) activity, used as a reliable index of inflammation caused by infiltration of activated neutrophils, was measured to quantify the colitis state." (PMID 18830146, 2008). "Therefore, we investigated MPO deficient mice in a murine model of colitis." (PMID 38673843, 2024).
colitis (continued). "It is noteworthy that DSS colitic mice express sepsis-like symptoms and that mice deficient in enzymes necessary for the respiratory burst (e.g., gp91) show significantly increased susceptibility to DSS colitis, suggesting that MPO may be redundant as an antimicrobial in mucosal inflammation." (PMID 39133648, 2024). "α-MSH-secreting L. casei showed a significant effect on attenuating acute colitis as assessed by body weight loss, intestinal damage score, MPO activity, pro- and anti-inflammatory cytokines levels, and survival rate; however, its efficacy relative to wild-type probiotics is unknown." (PMID 37049407, 2023). "Furthermore, oral administration of DeinoLys significantly reduced clinical symptoms against dextran sulfate sodium-induced colitis, including body weight loss, disease activity index, histological severity in colon tissue, and lower myeloperoxidase level in mice." (PMID 35719091, 2022). "Thus, the decrease in MPO and Nox-2 expression associated with persistent colitis in Eng+/− mice may lead to impaired ROS mediated bacterial clearance." (PMID 25114380, 2014). "Preemptive administration of TRF_12h markedly protected against colitis severity and fibrosis in CD models, as evidenced by marked reductions in F4/80+/MPO+ inflammatory cell infiltration and decreased extracellular matrix deposition." (PMID 41945859, 2026). "In DSS-induced colitis, KLF4 overexpression mitigated weight loss and disease activity, preserved colon length, improved histology, and reduced myeloperoxidase activity." (PMID 41918723, 2026). "EAE significantly increased the level of GSH and the activity of antioxidant enzymes, as well as it decreased the quantity of MDA and the activity of MPO compared to the colitis model group." (PMID 40699843, 2025). "To further investigate the relationship between MC and neutrophils in DSS-induced colitis in the presence of MPO and/or PAD4 inhibition, we next examined the extent of colon NETosis." (PMID 40459411, 2025). "MPO, a biomarker for neutrophil infiltration, increased significantly in the blood serum of the colitis mice, indicating severe neutrophils infiltration in the colon." (PMID 40115964, 2025). "Taken together, these data suggest that WMP administration can modulate MPO activity to support recovery from colitis." (PMID 40509652, 2025). "DSS-induced colitis increases the expression level of MPO while decreasing the concentration of antioxidative enzymes." (PMID 40452925, 2025). "Neutrophil infiltration in colonic tissue in colitis induced rat was indicated by elevated MPO activity and it was found to be reduced upon α-KG treatment in our study." (PMID 39886045, 2025). "Collagen peptides and Saccharomyces boulardii CNCM I‐745 reduced colon damage and significantly alleviated acetic acid‐induced colitis in rats by restoring ZO‐1 expression and suppressing MPO activity." (PMID 40255550, 2025). "This dysbiosis abolished the exercise-mediated suppression of NET formation, as evidenced by re-elevated levels of protein CitH3, MPO, and MPO-DNA complexes in exercised colitis mice following antibiotic treatment." (PMID 40585508, 2025). "In colitis, TH reduces colitis biomarkers such as MPO and pro-inflammatory cytokine IL-6, thereby mitigating inflammation." (PMID 40298838, 2025). "Expectedly, AVCP markedly reduced the serum MPO levels in colitis mice, which further supports the fact that AVCP exerts a potential therapeutic effect against UC." (PMID 40507195, 2025). "Recent reports have documented elevated NET levels in both patients with IBD and in experimental colitis models, where excessive NETs (marked by increased MPO and CitH3 levels) impair barrier permeability and exacerbate tissue damage." (PMID 40585508, 2025).
colitis (continued). "Colitis can also result in increased production of proinflammatory cytokines and myeloperoxidase (MPO), a lysosomal protein in neutrophils, which is a key indicator of neutrophil infiltration into colonic tissues during intestinal inflammation." (PMID 41322271, 2025). "In vivo, GLM exerted a protective effect in dextran sulfate sodium (DSS)-induced colitis models by decreasing Th1, Th2, and Th17 cells and myeloperoxidase (MPO) levels (a marker of neutrophil infiltration)." (PMID 41164200, 2025). "They observed an increase in anxiety-like behaviours and features of colitis including colon shortening, increased Myeloperoxidase (MPO) activity and Tumour Necrosis Factor (TNF) Alpha expression." (PMID 41462928, 2025). "For example, buthanol (BuOH) extracts of L. japonica improved IBD pathology in DSS-induced colitis mice by significantly reducing crypt injury, inflammation scores, and serum amyloid and MPO levels compared to 5-ASA." (PMID 40225345, 2025). "Experimental studies in murine colitis models have demonstrated that BA significantly attenuates myeloperoxidase (MPO) activity and lipid peroxide levels in colonic tissue while restoring catalase and superoxide dismutase (SOD) antioxidant functions." (PMID 40647158, 2025). "Fennel essential oil (200–400 mg/kg) also protected against acetic acid-induced colitis by reducing MPO activity, TNF-α expression, and NF-κB p65 phosphorylation." (PMID 41305003, 2025). "Improve clinical symptoms, inhibit myeloperoxidase and cytokines, and protect intestinal barriers in colitis mice and Caco-2 cells." (PMID 40225345, 2025). "Throughout this investigation, we found raised concentrations of MDA and MPO in colitis mice compared with control." (PMID 41476793, 2025). "MPO activity, a marker of neutrophil infiltration, was significantly elevated in the Colitis group (p < 0.01)." (PMID 40574090, 2025). "In a DSS-induced colitis mouse study, puerarin markedly reduced colon inflammation by inhibiting the NF-κB pathway—treated mice had significantly lower myeloperoxidase activity and reduced levels of TNF-α, IL-1β, and IL-6 in colonic tissue." (PMID 41008518, 2025). "Specifically, the abundance of Bacteroides and Escherichia-Shigella as opportunistic pathogens was significantly positively correlated with key pathological markers of colitis such as MPO, MDA, TNF-α, IL-6, and IL-1β." (PMID 41010513, 2025). "Studies in colitis-induced mice have shown that sleep deprivation aggravates gut inflammation, with histological damage and elevated tissue myeloperoxidase (MPO) activity." (PMID 41351111, 2025). "Mucosal myeloperoxidase activity and tumour necrosis factor α level as markers of colitis activity were also elevated." (PMID 41235209, 2025). "Homo (50 mg/kg) significantly alleviated colitis symptoms, lowered myeloperoxidase (MPO) activity, and improved histopathological outcomes." (PMID 40529132, 2025). "The study assessed weight, disease activity index (DAI) score, myeloperoxidase (MPO) activity, crypt length, inflammatory factors, and epithelial cell function in a mouse model of colitis treated with a UAF1 inhibitor." (PMID 39966502, 2025). "Myeloperoxidase (MPO) activity in colon tissue, a surrogate of neutrophil infiltration, was elevated ~2-fold in vehicle-treated colitis mice (p < 0.05)." (PMID 40869234, 2025). "Its efficacy is further established in vivo, where it alleviates TNBS-induced colitis in rats by suppressing myeloperoxidase (MPO) activity and oxidative stress." (PMID 41463524, 2025). "DSS-induced colitis is characterized by elevated MPO activity, pro-inflammatory cytokines (TNF-α, IL-6, IL-1β), and lipid peroxidation, alongside depleted antioxidant defenses (SOD, CAT, GSH)." (PMID 41395463, 2025). "CAEs IF (intestinal flora) treatment restored the colonic lengths, increased the body weight of the mice, and decreased DAI index, as well as a reduction in MPO activity of the colitis mice." (PMID 40994128, 2025).
colitis (continued). "Similar to the current findings, earlier studies have demonstrated that natural products reduce MPO activity to treat colitis." (PMID 40699788, 2025). "The results show that DSS-induced colitis led to significantly greater weight loss, shorter colon length, higher pathological scores, and increased MPO levels in the Mcpt-4ΔCre colitis mice as compared with the control Mcpt-4fl/fl colitis mice." (PMID 40697820, 2025). "The results show that HFO reduces the intensity and extent of colitis in rats by regulating the release of MPO and TNF-α, which has a protective effect on the mucosa." (PMID 40656621, 2025). "Our findings demonstrated that both gut microbiota remodeling and NDGA administration significantly attenuated colonic infiltration of myeloperoxidase (MPO)-positive neutrophils in the DSS-induced murine colitis model." (PMID 40596758, 2025). "Natural zinc-enriched oyster peptide significantly reduced MPO activity in the colonic tissues of DSS-induced colitis mice." (PMID 39997197, 2025). "MPO activity was also evaluated in a model of experimental colitis in mice as an indirect test for the analysis of neutrophil infiltration, and its activity was found to be reduced by RvD2 treatment." (PMID 40722934, 2025). "Blocking MPO activity pharmacologically has been shown to reduce disease symptoms in experimental colitis models." (PMID 40699843, 2025). "The outcome revealed that extracts help reduce edema in acute inflammation, decrease inflammatory cytokine levels in both the intestine and kidney, and decrease the number of leukocytes and MPO activity in colitis models." (PMID 40822453, 2025). "The UAF1 inhibitor significantly inhibited MPO activity in colon tissue and ulcer area, while significantly recovered crypt length in the mouse model of colitis (P < 0.01)." (PMID 39966502, 2025). "This resulted in the release of NE and MPO, leading to tissue damage and more severe colitis, even death." (PMID 41170289, 2025). "This study demonstrated that the damage related to colitis was associated with a significant increased levels of CRP and MPO activities in the colon." (PMID 40359212, 2025). "When AA was used to induce colitis, MPO enzyme activity increased significantly (p<0.01) compared to the sham group." (PMID 40656621, 2025). "Induction of experimental colitis resulted per se in the rise of MPO activity in the colon at the peak of the disease (PC vs. NC p < 0.05)." (PMID 40305159, 2025). "During the recovery phase of colitis, rutin significantly enhances the restoration of colonic crypts and goblet cells while reducing the activity of colonic myeloperoxidase (MPO)." (PMID 40395731, 2025). "MPO plays an essential role in colitis and is closely related to the development of inflammation and tissue damage." (PMID 38790796, 2024). "We observed the attenuation of the severity of colitis in mice treated with MC-170073, as indicated by the downregulation of macroscopic and histological scores along with lower levels of MPO and the proinflammatory cytokine IL-1β." (PMID 38713616, 2024). "Myeloperoxidase (MPO) serves as a marker for neutrophil infiltration in colon tissue following colitis induction." (PMID 39744127, 2024). "To evaluate the impact of SBP on inflammation in colitis, we measured the mRNA expression levels of various inflammation-related genes in colon tissue using RT-qPCR and the levels of myeloperoxidase (MPO) in plasma using a commercial kit." (PMID 38732527, 2024). "Given the elevated fecal lipocalin and cytokines at day 21, we extended our studies to interrogate the impact of MPO on chronic DSS colitis." (PMID 39133648, 2024). "Rosiglitazone treatment improved colitis, decreased MPO activity, and decreased the expression of TNF-α and ICAM-1 at the mRNA level." (PMID 39451206, 2024). "The MPO level was significantly elevated in the colitis mice model, indicating a substantial infiltration of neutrophils in the colon." (PMID 38790144, 2024).